CAD (carbamoyl-phosphate synthetase 2, aspartate transcarbamylase, and dihydroorotase)
Diseases named in the same sentence as CAD in open-access papers (continued):
Sharing a sentence is not in itself a finding about the gene and the disease.
tumor (continued). "DHODH and CAD expressions appeared greater in tumor tissues compared to adjacent tissues of HCC patients and were statistically significant." (PMID 37240659, 2023). "Taken together, these data show that l-CaD can interact with multiple signaling pathways that promote tumor progression and resistance to therapy." (PMID 36768598, 2023). "The IHC staining further confirmed that ASS1 was highly expressed in parenchyma cells in non-tumor tissues but reduced in HCC tissues while p-CAD expression was significantly elevated in HCC tissues." (PMID 35864952, 2022). "CAD knockdown resulted in a significant decline in tumor cell viability (P <0.05) and a marked decrease in the proliferative capacity." (PMID 35814473, 2022). "Targeting the β-catenin/AKT2/CAD axis repressed cell proliferation and tumor development driven by oncogenic β-catenin." (PMID 36122209, 2022). "Here, we provide first evidence that CAD protein is widely expressed among HCCs and is induced during tumor progression." (PMID 33670206, 2021). "The anti-tumour drug N-phosphonacetyl-L-aspartate (PALA) targets a domain of CAD in pyrimidine biosynthesis." (PMID 31795195, 2019). "CD2 downregulation not only directly impairs CTL activation and cytotoxicity but may also indirectly relieve the suppression of CAD expression in tumor cells by reducing IFN‐γ secretion, thereby promoting pyrimidine synthesis." (PMID 40859981, 2025). "However, the effects of 5-FU interventions on CAD cleavage, as well as the extension of the lifespan of tumor-bearing mice, were all attenuated in the mice with CadD1371A/D1371A knockin." (PMID 40442064, 2025). "In the past years, both tumor-inhibiting and promoting roles of CAD had been reported." (PMID 40849416, 2025). "The core enzyme CAD, which is involved in the de novo synthesis of pyrimidines, is essential for maintaining proper levels of pyrimidine nucleotides in cells and for anti-tumor immunomodulatory effects." (PMID 38517376, 2024). "Western blot analysis of tumor homogenates from the orthotopic VCaP xenografts also showed a trend of increase in both GR and l-CaD expression in the tumors treated with the antiandrogen (apalutamide), although the expressions were heterogeneous as expected based on our IHC analyses." (PMID 37573448, 2023). "In summary, our data suggest that antiandrogen resistance may give rise to colonies of GR-upregulated PCa cells within the tumor where l-CaD expression is induced in response to GR activation in the absence of AR signaling." (PMID 37573448, 2023). "In addition, increased phosphorylation of CAD has been observed in a variety of tumors, which stimulates tumor growth by initiating the first three reactions of pyrimidine de novo synthesis." (PMID 35864952, 2022). "However, we found that CAD knockdown suppressed the in vivo tumor growth much more significantly than DHODH knockdown." (PMID 30643150, 2019). "Although the in vivo tumor cells often grow in a hypoxic microenvironment, whether their ammonia production will be affected by CAD knockdown remains unclear due to the inefficient tumor formation of cancer cells with shCAD." (PMID 30643150, 2019). "However, as the important role of CAD in cellular apoptosis, simply depleting CAD might reduce its effects on tumor suppression because of impaired apoptosis." (PMID 40849416, 2025). "In addition to supplying cytoplasmic aspartate for increased CAD activity, the overexpression of citrin in tumor cells could lead to metabolic reprogramming in tumor cells through the disruption of the malate-aspartate shuttle and energy production." (PMID 37047726, 2023). "To evaluate the impact of CAD on tumor growth in vivo, we established cell-derived xenografts in nude mice via Huh-1 and HCCLM3 cells depleted of CAD." (PMID 40289107, 2025).
tumor (continued). "Although this study did not specify which CaD isoform was detected particularly by expression analysis, we and others have shown that l-CaD, but not h-CaD, is unequivocally expressed in carcinoma cells using multiple techniques, in addition to its expression in the tumor-associated stroma." (PMID 36768598, 2023). "CAD activation requires MAPK, so it is possible that carfilzomib indirectly inhibits CAD by suppressing MAPK signaling and promoting an anti-tumor response." (PMID 35814473, 2022). "The results showed that the expression of ASNS was correlated with the size of tumor growth,that of CEBPA was correlated with the gender of patients and TNM stage of tumor, and that of CAD was highly correlated with recurrence and metastasis." (PMID 35174151, 2022). "Western blot analyses of ASS1 and phosphorylated CAD (p-CAD) in 12 paired clinical samples revelated that compared to non-tumor liver samples, ASS1 was notably downregulated, whereas CAD activation (p-CAD/CAD ratio) was upregulated in HCC tissues." (PMID 35864952, 2022). "For example, resistance to rituximab and doxorubicin was conferred by CRISPRi of SMARCE1, a known tumor suppressor in DLBCL and other cancers, and by CRISPRi of CAD, a protein involved in pyrimidine biosynthesis whose knockdown causes S phase arrest." (PMID 31742555, 2019). "CAD and POLD2 were significantly correlated in BLCA tumor samples; however, when restricted to patients administered cisplatin-based therapy, patient expressions became more tightly correlated (r = 0.45, P < 0.001 vs r = 0.61, P < 0.001, respectively)." (PMID 30038717, 2018). "The size of the primary tumor was not changed after l-CaD knockdown, suggesting a specific effect pertaining to the metastasis process." (PMID 37573448, 2023). "Targeting enzymes involved in pyrimidine synthesis, such as CAD protein (carbamoyl-phosphate synthetase 2, aspartate transcarbamylase, and dihydroorotase) and DHODH, inhibited GSC survival and self-renewal and reduced tumor growth in rodent models." (PMID 37298093, 2023). "Previous studies have found that either inhibiting CAD or DHODH, or direct targeting of pyrimidine metabolism, could inhibit tumor progression." (PMID 37240659, 2023). "Importantly, we demonstrated that UBE2T was positively correlated with p-Akt, β-catenin, CAD, DHODH, and UMPS in HCC tumor tissues." (PMID 35169125, 2022). "Although we detected CAdTrio-derived IL-12p70 in the blood, we found local CAd treatment had no additive anti-tumor effect in CFPAC-1 xenograft mice." (PMID 33742099, 2021). "The level of CAD is correlated with the rate of cell division; two to five-fold higher levels in tumor cells than in normal cells and almost non-existent in quiescent cells." (PMID 18560559, 2008). "We revealed that CAD directly interacts with STING to block STING dimerization/polymerization and binding to cGAMP, resulting in retention of STING at endoplasmic reticulum (ER), reduction of IFN-Is and chemokines and the subsequent less infiltrated lymphocytes in tumor." (PMID 40849416, 2025).
cancer (63 papers, 2010 to 2026). A tumor composed of atypical neoplastic, often pleomorphic cells that invade other tissues. "In HNSCCs other than OSCC, the expression of CAD is positively associated with that of glycolytic genes, and CAD antagonists inhibit cancer cell survival." (PMID 39201614, 2024). "While our preliminary results support CAD as a metabolic vulnerability for KSHV-infected cells, extensive future research will be needed to assess the association between a dysregulated CAD and cell susceptibility to CAD inhibitors in more types of cancers." (PMID 38365882, 2024). "The causality of the CTNNB1 mutation and hepatocarcinogenesis thus confers AKT2/CAD signaling cascade-mediated pyrimidine synthesis a druggable vulnerability for CTNNB1 mutant cancer." (PMID 36122209, 2022). "Deregulation of CAD-related pathways or CAD mutations cause cancer, neurological disorders, and inherited metabolic diseases." (PMID 34638594, 2021). "Besides, C-Myc, a hallmark of human cancers, also up-regulates CAD expression by binding with CAD E-box sequence in cancer cells." (PMID 34638594, 2021). "Post-radiation, cancer cells activate CAD (Caspase-Activated DNAse), leading to DNA fragmentation and G2 arrest, providing additional time for repair." (PMID 41424847, 2026). "The caspase-3-mediated cleavage and degradation of CAD is a necessary step for the death of cancer cells induced by chemotherapy drugs in GC and CRC." (PMID 40442064, 2025). "This possibility has attracted the interest of cancer researchers to explore the role of CaD in cancer development." (PMID 36768598, 2023). "The modulation of DHODH activity in cancer focused on activating the biosynthesis of de novo pyrimidine biosynthesis through CAD complex." (PMID 36524129, 2022). "The inhibition of CAD to impair pyrimidine de novo synthesis in the first committed step from glutamine was thought to be a promising strategy in cancer already in the early 1970s." (PMID 35203388, 2022). "Targeting CAD or the critical downstream enzyme DHODH via alleviating carbon influx through pyrimidine synthesis inhibited cancer cell survival, self-renewal." (PMID 34638594, 2021). "(i) Carbamoyl-phosphate synthetase 2 (CAD), the rate limiting enzyme in the pyrimidine biosynthesis pathway, was upregulated in both cancer and non-cancer cell lines." (PMID 32365991, 2020). "Below, we discuss the key known factors involved in the regulation of CAD, many of which can be overactive in cancers." (PMID 33020720, 2020). "TTN and CAD were identified as mutated oncogenes; TTN ranks at the top of 518 potential protein kinase cancer genes and it encodes the largest polypeptide that is expressed in many functional cell types in oncogenesis." (PMID 30786925, 2019). "Our in vitro data showed that knockdown of CAD enhanced ammonia excretion from cancer cells under hypoxia." (PMID 30643150, 2019). "The regulation of CaD is important for proper cell function because decreased expression of l-CaD has been found in many cancer cell types." (PMID 26079947, 2015). "CaD is known to play an essential role in actin cytoskeletal dynamics and cell contraction, but little is known regarding its functions in cancer cells." (PMID 26079947, 2015). "In k-FGF transfected cancer cells that developed resistance to methotrexate, CAD and DHFR were the main genes responsible for the resistance." (PMID 22905093, 2012). "More recently it was reported that expression of CaD suppresses the invasive activity of cancer cells." (PMID 20128924, 2010). "Moreover, CAD-mediated pyrimidine biosynthesis is not only essential for cancer progression but also plays a role in immune evasion, as some studies suggest a correlation between pyrimidine metabolism and immune checkpoint activity." (PMID 39941127, 2025).
cancer (continued). "This axis has been implicated in cancer metabolism; for instance, Gln is a potent precursor of nucleotide biosynthesis through the carbamoyl phosphate synthetase-II (CPS-II), aspartate transcarbamylase (ATCase) and Dihydro orotase (CAD) enzyme system." (PMID 38268823, 2024). "In addition, UCD-associated arginine synthesis reduction elicits a 'metabolic shift', which recycles ammonia to glutamine and upregulates CAD activation to enhance de novo pyrimidine synthesis, promoting cancer initiation and progression." (PMID 35864952, 2022). "In addition, cancer cells cultured in hypoxia shunt amide nitrogen from glutamine into pyrimidine synthesis through upregulation of CAD." (PMID 35629973, 2022). "Simultaneous inhibition of uridine salvage with cyclopentenyl uracil and pyrimidine de novo synthesis with the CAD inhibitor PALA increased cancer cell death in mouse models further highlighting the impact of nucleoside salvage on the efficacy of anti-cancer agents targeting de novo synthesis." (PMID 35203388, 2022). "CAD, as a downstream of mTORC1, has proved that its activity is a prerequisite for cancer cells to synthesize nucleic acids, and perturbation of nucleic acid biosynthesis can result in cancer cell death." (PMID 34638594, 2021). "Regarding pyrimidine metabolism, the upregulation of CMPK1, CMPK2, CTPS2, CAD, DHODH, and UMPS suggests a role in supporting placental growth under stress, reflecting their established functions in cancer cell proliferation." (PMID 40825832, 2025). "This was further supported by demonstration of increased CAD (carbamoyl-phosphate synthetase 2, aspartate transcarbamylase, and dihydroorotase) activity in ASS1 silencing cancer cells." (PMID 33500708, 2021). "Upregulation of the metabolic genes (ALDH18A1, CAD, CHKA, POLD4, PSPH, and SQLE) and aberrant expression of cancer-related genes (ALCAM, ITGA6, DDIT3, MAP3K6, and PAK1) were found in mouse fed with high-fat-high-cholesterol similar to human NASH-HCCs." (PMID 31795276, 2019). "We demonstrated for the first time the aberrant expression of cancer-related genes (ALCAM, ITGA6, DDIT3, MAP3K6 and PAK1) and metabolism-related genes (ALDH18A1, CAD, CHKA, POLD4, PSPH, SQLE and CFD) in human NASH-HCCs." (PMID 30367044, 2018). "Gene expression analysis also revealed that the expression of pro-apoptotic genes such as Bax, Bak, AIF, NOXA1, CAD, PARP and cytochrome c were increased when cancer cells were treated with gossypol." (PMID 23226540, 2012). "Although the CAD with the Asp1371 mutation did not enhance the binding to previously reported interacting proteins, nor did it increase the de novo synthesis of pyrimidine nucleotides, whether the mutated form of CAD exhibits any other functions in cancer cells remains unknown to us." (PMID 40442064, 2025). "As part of another treatment strategy for cancer metabolism, most research have been concentrated inhibiting enzymes related to UMP synthesis, with a particular focus on drugs targeting DHODH (e.g., leflunomide) and CAD enzymes." (PMID 38704578, 2024). "Additionally, the reduction of another enzyme in cancers, argininosuccinate synthase (ASS1), as well as CPS1, elevates cytosolic aspartate levels, thus providing substrates to CAD by facilitating pyrimidine synthesis." (PMID 34638594, 2021). "PALA (N-phosphonacetyl-l-aspartate), an inhibitor of the aspartate transcarbamoylase activity of CAD, was tested in cancer patients in the 1980s but did not make it beyond a phase II trial." (PMID 33020720, 2020). "However, knockdown of CAD or GOT1 strongly, while DHODH knockdown marginally, sensitized cancer cells to hypoxia." (PMID 30643150, 2019). "CAD is a multifunctional (the trifunctional rate-limiting enzyme of the de novo pyrimidine synthesis pathway) protein catalyzing the first 3 steps of pyrimidine biosynthesis, but its role or regulation in cancer remains not well characterized." (PMID 40190348, 2025).
cancer (continued). "L-CaD is widely distributed in non-muscle cells, and studies have shown that l-CaD promoted malignancy in several cancers." (PMID 33996905, 2021). "Therefore, the blood dihydroorotate/orotate may be a potential biomarker for cancer diagnosis, and the involved metabolic enzymes, such as CAD and GOT1, could be potential targets for cancer treatments." (PMID 30643150, 2019). "To study the role of l-CaD in cancer cell migration and invasion in vivo, we injected mCherry PC3 cells transfected with siRNAs targeting l-CaD or non-targeting siRNAs into zebrafish larvae yolk sacs and assessed the formation of metastases after four days." (PMID 37573448, 2023). "A beguiling question is why cancer cells seem to rely mainly on DHODH and not on CAD, which catalyzes half of the reactions in the de novo pyrimidine synthesis pathway." (PMID 31108873, 2019). "Even though this decreasing trend in the amplified transcription of SAMHD1 at 24 h might result in loosening the regulation of CAD, DHODH and UMPS, the critical enzymes involved in direct influx of dTMP (TYMS and TYMP) did not appear to be recovered to normal levels in cancer cells." (PMID 36414668, 2022). "Thus, it is unclear as to whether CAD is not sufficiently inhibited by PALA and its analogues, or if this enzyme is not a suitable target for cancer treatment." (PMID 33020720, 2020). "Indeed, independent of arginine importance, cancer cells become more proliferative when ASS1 is silenced because of the increased cytosolic availability of its substrate, aspartate, for pyrimidine synthesis by CAD (carbamoyl-phosphate synthase 2, aspartate transcarbamylase and dihydroorotase)." (PMID 30082427, 2018).